EZH2 (enhancer of zeste 2 polycomb repressive complex 2 subunit)
Diseases named in the same sentence as EZH2 in open-access papers (continued):
Sharing a sentence is not in itself a finding about the gene and the disease.
tumor (continued). "Previous studies indicated that EZH2 is involved in regulating the proliferation and invasion of multiple cancer cells by suppressing tumor suppressor genes or the transcription of microRNAs." (PMID 24967960, 2014). "Currently, EZH2 has been found to function as a transcriptional repressor that silences an array of target genes, including more than 200 tumor suppressors." (PMID 25159232, 2014). "Immunostaining of resected tumor tissues found that tumors formed from sh-EZH2-transfected SPC-A1 cells exhibited decreased positivity for Ki67 than those from control cells." (PMID 24967960, 2014). "Recently, a newly identified mechanism has been observed, which proves that EZH2 plays a crucial role in tumor angiogenesis." (PMID 25237831, 2014). "As a catalytic subunit of PRC2, EZH2 is primarily considered as an epigenetic silencer for transcriptional repressing of gene expression, including a variety of tumor suppressor genes." (PMID 25520914, 2014). "In this study, we employed the X-tile program to select the optimal cutoff points and found that more than 50% of tumor cells showed high expression of Ring1B and EZH2." (PMID 25431952, 2014). "The alteration in H3.3 which inactivates EZH2 and global DNA hypomethylation suggests that two regulatory pathways that communicate to maintain normal brain development are altered in this tumor type, leading to an unopposed active transcriptional state." (PMID 24894482, 2014). "By multivariate stepwise logistic regression analysis, we found low expression of EZH2 showed significant correlation with good tumor regression (OR = 2.684; 95% CI 1.147-6.280, p = 0.023) and down staging (OR = 2.476; 95% CI 1.107-5.537, p = 0.027)." (PMID 25159232, 2014). "The abnormalities of EZH2 were observed to correlate closely with tumor aggressiveness and/or poor patient prognosis." (PMID 25036033, 2014). "EZH2 is a master regulatory gene that has a critical role in cancer development through its ability to epigenetically silence tumor suppressor genes." (PMID 25153722, 2014). "In particular, the methylase EZH2 functions as an oncogene in different human cancers mainly through epigenetic silencing of tumor and metastasis suppressor genes, including E-cadherin, RUNX3, SLIT2, DAB2IP, FBXO32, and KLF2." (PMID 24852755, 2014). "When analyzing expression differences in the study cohort as a whole, only median H3K27me3 and EZH2 expression were significantly different between tumor and normal tissues (p<0.001 and p = 0.05, respectively)." (PMID 25243792, 2014). "We show here that it is possible to revert the tumor phenotype of the RD cell line by silencing EZH2 even under proliferative stimuli such as in a serum-enriched molecular context." (PMID 24575771, 2014). "Our results demonstrate that SAHA and DZNep suppress EZH2 expression and activate tumor-suppressor miRNAs in cancer cells." (PMID 24861464, 2014). "EZH2 has been shown to regulate tumor suppressor genes and miRs through histone H3K27 trimethylation marks at their promoters." (PMID 25115393, 2014). "Elevated expression of EZH2 correlates with tumor malignancy, poor prognosis and poor patient survival." (PMID 25520914, 2014). "EZH2 downregulation can reduce growth of invasive breast carcinoma, tumour angiogenesis and in vitro cell migration/invasion of CRC cell lines." (PMID 25549357, 2014). "Upregulation of EZH2 in tumor cells, which is common in both hematopoietic malignancies and solid tumors, promotes cell growth, migration and invasion." (PMID 25237831, 2014). "Disruption of EZH2 expression was observed to correlate closely with tumor aggressiveness and/or poor patient prognosis in prostate, oral, bladder, esophageal, breast and ovarian cancers." (PMID 25159232, 2014). "This resulted in the up-regulation of EZH2-silenced tumor suppressor genes, including CDKN1C, DAB2IP, and WNT5a, in a dose-dependent manner in multiple cancer cell lines (e.g., T24, MBT2, and PC3)." (PMID 25431950, 2014).
tumor (continued). "It is interesting to know if EZH2 has a role in the “cancer stem cell” driving force behind tumor proliferation and progression." (PMID 25431950, 2014). "Given that EZH2 directly targeted Ink4a/Arf, a tumor suppressor locus that is frequently inactivated in human GBM, it is possible that EZH2 in SVZ astrocytes increases their oncogenic potential." (PMID 24867641, 2014). "SMARCB1 is a subunit of the ATP-dependent chromatin remodeling complex SWI/SNF, a powerful epigenetic tumor suppressor, which directly antagonizes the histone methyltransferase EZH2." (PMID 24983247, 2014). "Most such mutations are nonsense and stop codon mutation, resulting in loss of HMTase activity, apparently unlike Y641 and A677 mutants, raising the possibility for EZH2 acting as a tumor suppressor." (PMID 25520914, 2014). "Tumor tissues showed higher expression of EZH2 (p = 0.05) and H3K27me3 (p<0.001) as compared to their normal counterparts." (PMID 25243792, 2014). "One of the targets of EZH2 is the prostate tumor suppressor NKX3.1 as well as other Homeobox genes promoters." (PMID 25277175, 2014). "EZH2 overexpression in various cancers correlates with tumor aggression and can serve as a prognosis indicator." (PMID 25359725, 2014). "Functional studies showed that EZH2 upregulation promoted cell proliferation, migration and tubule formation of endothelial cells, and knockdown of EZH2 suppressed tumor growth, metastasis and angiogenesis in vivo." (PMID 25237831, 2014). "In many different types of cancer, PcG proteins, such as EZH2, are expressed at higher than normal levels, which is thought to lead to aberrant silencing of tumor suppressor genes." (PMID 25333635, 2014). "A component of polycomb repressor complex 2, enhancer of zeste homolog 2 (EZH2), plays an important role in tumor malignancy and metastasis, while milk fat globule-epidermal growth factor-factor 8 (MFGE8) plays a key role in tumor progression and prognosis." (PMID 25081869, 2014). "EZH2 expression in biopsy tissue was significantly related to increased tumor cell proliferation, as assessed by Ki-67 expression with a cutoff value of 37% (p <0.001)." (PMID 25159232, 2014). "It is likely that gene regulatory networks controlled by Ezh2 in tumor endothelial cells differ from those in embryonic endothelial cells during the formation of blood vessels." (PMID 25359725, 2014). "EZH2, an enzymatic component of PRC2, was shown to be overexpressed in metastatic cancer, and the expression levels were associated with tumor progression." (PMID 25542019, 2014). "Results showed two SNPs of EZH2 decreased UCC susceptibility, and UCC patients with the polymorphism rs2302427 had a lower risk of invasive tumor stage." (PMID 24691023, 2014). "We confirm a functional oncogenic role for EZH2 in SCLC, and an associated and DNA hypermethylator profile for SCLC tumours." (PMID 23967231, 2013). "Here, we investigated the functional role of EZH2 in IBC cells by examining the effects of its knockdown on the formation of tumor spheroids and invasion of these cells in vitro and in vivo in an orthotopic xenograft model." (PMID 24294976, 2013). "Re-expression of miR-101 inhibits the expression of EZH2 and attenuates cell proliferation and tumor invasiveness." (PMID 24202331, 2013). "The tumor suppressive function of miR-101 has been corroborated by its inhibitory effect on EZH2, an oncogene of many solid tumors." (PMID 24013378, 2013). "Knockdown of the predominant H3K27 methyltransferase, enhancer of zeste 2 (EZH2), in a mouse mammary xenograft model significantly reduced tumor burden in these animals and demonstrated the predictive utility of proteomic techniques." (PMID 23826629, 2013).
tumor (continued). "The action of HYP is shown to modify aberrant parameters in the tumorigenic epigenetic code, downregulating expression of class I HDACs and EZH2 in GBM tumor cell lines." (PMID 24066060, 2013). "Down-regulation of EZH2 significantly impeded tumor growth and inhibited lung and liver metastasis in vivo." (PMID 24062983, 2013). "When the levels of Nanog are high and those of EZH2/H3K27me3 are low, the cells exhibit self-renewal activity—that is, they multiply and a tumor can develop." (PMID 24313165, 2013). "EZH2-mediated epigenetic control, known for protein-coding genes, also occurs on the miRNA loci, as demonstrated in many tumours." (PMID 24351808, 2013). "miR-101 has mainly been studied for its tumor suppressive functions, by directly targeting EZH2, Cox-2, Mcl-1 and Fos." (PMID 23414127, 2013). "Together, our results suggest that expression levels of EZH2 positively correlates with tumor spheroid formation and tumorigenicity in this new IBC cell line." (PMID 24294976, 2013). "One important pro-metastatic role of EZH2 in cancer is via epigenetic silencing of tumor and metastasis suppressor genes." (PMID 23826380, 2013). "Two HDAC inhibitors have been approved for the treatment of T-cell lymphomas, and EZH2 depleting drugs, such as DZNep, have anticancer activity in vitro for multiple tumor types." (PMID 24079712, 2013). "The importance of targeting EZH2 in NB was first noted with our finding that targeted inhibition of EZH2 leads to induction of genes having tumor suppressive or differentiation inducing capacity." (PMID 23373009, 2013). "Based on these results, we conclude that knockdown of EZH2 suppresses the proliferation and tumor spheroid growth of human IBC cells in vitro." (PMID 24294976, 2013). "Functionally EZH2 was reported to suppress a number of genes with tumor suppressor activity in NB including the MYCN-regulated genes CLU and p75(NGFR)." (PMID 23373009, 2013). "Enhancer of zeste homolog 2 (EZH2) has been shown to contribute to tumour development and/or progression." (PMID 23874688, 2013). "There is increasing evidence that overexpression of the EZH2 gene occurs in a variety of human malignancies, and abnormalities of this gene correlate closely with tumour aggressiveness and/or poor patient prognosis." (PMID 23874688, 2013). "In total, 49 cases were scored for expression of EZH2 and the remaining cases were excluded from further analyses because of insufficient tumor size or due to artifacts." (PMID 24266940, 2013). "EZH2 overexpression occurs in many different cancers, where it acts as a classical oncogene that can promote tumor formation by silencing several tumor suppressor genes, such as E cadherin." (PMID 24313165, 2013). "EZH2 functions as an oncogene in different human cancers mainly through epigenetic silencing of tumor and metastasis suppressor genes, including E-cadherin, RUNX3, SLIT2, DAB2IP, and KLF2." (PMID 23826380, 2013). "In the present study, we examined the expression of the components of PRC2 in human IBC cells, as well as the effects of EZH2 knockdown on the formation of tumor spheroids, invasion and tumor growth of human IBC cells." (PMID 24294976, 2013). "The major finding of this study is that the EZH2 knockdown significantly suppressed the formation of tumor spheroids in vitro (a characteristic of IBC cancer stem cells), and tumor growth in vivo in a new human IBC model." (PMID 24294976, 2013). "HYP induces unique epigenetic down-regulations of HDACs, EZH2 and DNMTs, remodeling chromatin structure and culminating in tumor cell differentiation." (PMID 24066060, 2013). "EZH2 expression was detected in tumor cells by immunohistochemistry in paraffin-embedded samples of GBM (five of five samples); no detectable expression was observed in adjacent brain parenchyma." (PMID 24202337, 2013). "Consistent with the role of PcG in deterring tumor development, upregulation of EZH2 leads to aggressive progression of both breast and prostate cancers." (PMID 24172544, 2013).
tumor (continued). "Treatment of rhabdoid tumor cell line A204 with SAHA upregulates RB- and MYC- target genes and the pluripotency-associated program controlled by EZH2." (PMID 23764045, 2013). "Tumor cells of all cases exhibited EZH2 nuclear staining, but the proportion of EZH2 expression varied." (PMID 24266940, 2013). "With the emerging concept of tumor stem cells it has subsequently become clear that EZH2 similarly controls expansion and differentiation of tumor initiating cells and contributes to the development and progression of cancer." (PMID 23077658, 2012). "Our data indicate that EZH2 expression in tumor relative to adjacent normal lung tissue is a strong and independent predictor of the clinical outcome in these patients." (PMID 23300840, 2012). "Accumulated evidence shows that EZH2 is deregulated in a wide range of cancer types, and it has a crucial role in stem cell maintenance and tumour development." (PMID 22187039, 2012). "We also demonstrated that tumor-specific up-regulation of EZH2 mRNA expression is an independent factor for poor survival in patients with NSCLC." (PMID 23300840, 2012). "Kaplan-Meier analysis showed that patients whose tumors had high tumor EZH2 expression relative to paired adjacent normal lung tissue had a significantly inferior clinical outcome compared to those whose tumors had low EZH2 expression." (PMID 23300840, 2012). "Further validation of E-cadherin expression through IHC revealed a significant decrease in E-cadherin expressing tumor cells in LN metastasis compared to paired primary tumor, which coincided with an up-regulation of EZH2 in LN metastasis." (PMID 23251464, 2012). "The proportion of EZH2 expressing tumor cells in lymph nodes was significantly higher compared to matched primary tumor cells (p = 0.039)." (PMID 23251464, 2012). "For example, disruption of EZH2 by DZNep or by short-hairpin RNAs (shRNAs) was shown to significantly impair self-renewal and the tumour-initiating capacity of glioblastoma cancer stem cells or ovarian cancer stem cell-like populations." (PMID 22187039, 2012). "On the other hand, the expression level of EZH2 protein was upregulated in tumor in 92.5% (37/40) of specimens with a total average of 2.6 fold increase than in the matched normal tissues." (PMID 22867052, 2012). "Paired-Wilcoxon signed rank test showed a significant increase of EZH2 in metastatic tumor cells compared to primary tumor cells (p = 0.007); EED demonstrated an increased trend in 6 out of 8 paired samples (p = 0.054)." (PMID 23251464, 2012). "EZH2 mRNA appeared to be higher in tumor than in the normal tissue in 60% (24/40) of specimens, but overall the difference in EZH2 mRNA expression between ESCC tissues and the matched normal tissues was not statistically significant." (PMID 22867052, 2012). "It was found that 75% (30/40), 62.5% (25/40), and 85% (34/40) of samples showed downregulation of miRNAs (i.e. miR-98, miR-101 and miR214) with upregulation of EZH2 protein in tumor versus normal tissues, respectively." (PMID 22867052, 2012). "The aim of this study was to determine the role of these miRNAs in the regulation of tumor metastasis via EZH2 overexpression in human ESCC." (PMID 22867052, 2012). "The immunohistochemical demonstration of Enhancer of zeste homologue 2 (EZH2) proved to be a useful marker in several tumor types." (PMID 22809481, 2012). "High levels of EZH2 were shown to be associated with poor clinical outcome in other tumor types as well, and the mechanisms that link EZH2 activity with tumor progression are gradually being unfolded." (PMID 23110793, 2012). "Downregulation of EZH2 by shRNAs in vivo significantly decreased breast xenograft tumour growth and improved survival." (PMID 22187039, 2012). "Cases with high EZH2 score were characterized by larger tumor size (≥ 5cm), distant metastasis, and poor prognosis." (PMID 23110793, 2012).
tumor (continued). "Ezh2 silencing in tumor endothelial cells results in decreased angiogenesis mediated by increased levels of the angiogenesis inhibitor, VASH1." (PMID 23109879, 2012). "By microarray network analysis, we found an increased expression of polycomb repression complex 2 (PRC2) core subunits EED and EZH2 in lymph node metastatic tumor cells over primary tumor cells which were validated through real-time PCR." (PMID 23251464, 2012). "It was found that the expression level of EZH2 protein was significantly higher in tumor tissues than in matched normal tissues, despite that EZH2 mRNA expression was comparable between the two groups." (PMID 22867052, 2012). "Peptides STEAP281-296 and EZH295-109 function as strong CD4 T-cell epitopes that can elicit effective anti-tumor T-cell responses against STEAP or EZH2 expressing LC." (PMID 22053850, 2011). "Along the same lines, our group showed that EZH2 expression is increased in tumor tissues from RMS patients independently of histological subtype, and correlates with markers of poor prognosis (Abstract # 10-A-4051 AACR 2010)." (PMID 21943149, 2011). "EZH2 is highly expressed in various tumor types including prostate, breast, esophagus, and pancreatic cancers." (PMID 22053850, 2011). "EZH2 plays a role in cell cycle regulation and proliferation and increased EZH2 expression has been correlated with aggressive tumor behavior and poor survival in LC." (PMID 22053850, 2011). "Median tumour weights of mice receiving T cells were significantly lower compared with control mice (P=0.015 for EZH2- and 0.039 for CHM1 study group, respectively, compared with controls, Welch two sample t-test)." (PMID 21407224, 2011). "Specifically, for certain cancer entities, it has been reported that EZH2 stimulates cell proliferation, blocks apoptosis, promotes cell invasion and metastasis, activates tumor angiogenesis, and induces tumors in mouse models." (PMID 21765901, 2011). "Downregulation of EZH2 by RNA interference suppressed ET tumour development and metastasis in immunodeficient Rag2−/−γC−/− mice." (PMID 21407224, 2011). "Peptides STEAP281-296 and EZH295-109 are newly described CD4 T-cell epitopes that can elicit effective anti-tumor T-cell responses against STEAP or EZH2 expressing LC cell lines." (PMID 22053850, 2011). "Data from these studies offer an example of how a translocation-derived fusion product takes advantage of EZH2 recruiting this methyltransferase to drive tumor progression at the expenses of differentiation." (PMID 21609503, 2011). "Apart from EZH2, tumor stage and high Fuhrman's grading (3/4 vs. 1) emerged as significant prognostic indicators, whereas sex, Karnofsky performance status, age, and histopathological subtype did not independently predict the clinical outcome." (PMID 20920340, 2010). "Ezh2 knockdown by small interfering RNA (siRNA) decreases prostate cell proliferation and inhibits the metastatic tumor growth of PC-3 cells in bone tissue." (PMID 20478051, 2010). "After tumor cell implantation, we injected one set of mice (n = 5) intravenously with the EZH2 inhibitor DZNep (0.07 mg/kg) and a parallel control set (n = 5) with PBS only, at day 3, 5, and 7, followed by weekly injection." (PMID 21321380, 2010). "Apart from high nuclear EZH2 expression, tumor stage and Fuhrman's grading emerged as significant prognostic markers." (PMID 20920340, 2010). "Although EZH2 knock down was shown to be embryonic lethal in mice, knock down of EZH2 in cancer cells resulted in growth arrest, as well as in diminished tumor growth and reduced metastasis in vivo." (PMID 21321380, 2010). "Inhibition of EZH2 in vivo by systemic DZNep administration in a U87-Fluc-mCherry GBM xenograft mouse imaging model resulted in reduced tumor growth." (PMID 21321380, 2010). "Multivariate Cox regression analyses on RCC outcome included tumor stage, Fuhrman's grading, Karnofsky performance status, age, sex, histopathological subtype, and EZH2 expression." (PMID 20920340, 2010).